SOD1 (superoxide dismutase 1)
Diseases named in the same sentence as SOD1 in open-access papers (continued):
Sharing a sentence is not in itself a finding about the gene and the disease.
sarcopenia (40 papers, 2013 to 2026). Progressive decline in muscle mass due to aging which results in decreased functional capacity of muscles. "Mice with a muscle-specific SOD1 mutation develop fiber atrophy, loss of strength, and mitochondrial dysfunction, thus becoming a potential model for sarcopenia." (PMID 39062745, 2024). "In a similar manner, young mice deficient in Superoxide dismutase 1 (Sod1) age prematurely and develop severe sarcopenia." (PMID 27630760, 2016). "This hypothesis is sustained by previous observations on pre-clinical models, in which SOD1 depletion causes early sarcopenia, or CAT overexpression reduces the age-dependent loss of muscle quantity and performance." (PMID 38001845, 2023). "The absence of the cytosolic SOD1 isoform is known to significantly decrease lifespan and more recently, high levels of oxidative stress and accelerated sarcopenia due to O2 ̅ induced neuromuscular degeneration and mitochondrial dysfunction has been shown in SOD1 deficient mice." (PMID 24093947, 2013). "However, it is noteworthy to underline that SOD1 is secreted as well, and, therefore, the elevated extracellular oxygen radical, associated with sarcopenia, could also be scavenged by cytosolic SOD1." (PMID 31387214, 2019). "In this study, we examined a copper zinc superoxide dismutase [CuZnSOD (Sod1)] knockout mouse (Sod1−/−), a mouse model of elevated oxidative stress that exhibits accelerated loss of muscle mass, which recapitulates many phenotypes of sarcopenia as early as 5 months of age." (PMID 24971750, 2014). "Perturbations to muscle mitochondrial signaling through overactivation of mTORC1 or loss of the antioxidant enzyme superoxide dismutase 1 (SOD1) induces sarcopenia‐like features in NMJs such as denervation, fragmentation of AChRs, and loss of muscle function." (PMID 41496579, 2026). "Studies using Sod1–/– mice are similar with respect to the sarcopenia observed in aging mice in general, such as oxidative stress, NMJ denervation, AChR fragmentation, and muscle atrophy." (PMID 40313092, 2026). "Results from preclinical studies showed accelerated sarcopenia in transgenic mice knocked out for the antioxidant enzyme superoxide dismutase 1 (SOD1)." (PMID 38396729, 2024). "In fact, Cu/Zn superoxide dismutase (SOD1)-knockout mice show accelerated loss of muscle mass and function due to increased ROS generation, resulting in the loss of muscle fibers and sarcopenia." (PMID 35955849, 2022). "Mice with a muscle-specific SOD1 mutation (SOD1G93A) develop fiber atrophy, loss of strength, and mitochondrial dysfunction, making it a possible model for sarcopenia." (PMID 34445751, 2021). "If mitochondrial dysfunction contributes to sarcopenia, muscles of i-mn-Sod1-/- mice should display mitochondrial dysfunction by middle age." (PMID 34639076, 2021). "Our results suggest that PIC protects skeletal muscles from oxidative stress by activating antioxidant enzymes such as HO-1 and SOD1 and can therefore help prevent oxidative stress–induced muscle dysfunction such as muscle fatigue and sarcopenia." (PMID 31080897, 2019). "It was proposed that sarcopenia in Sod1−/− mice may result from a two-hit mechanism affecting both skeletal muscle and motor neurons." (PMID 40869107, 2025). "Moreover, animals expressing muscle-specific mutated forms of SOD1 (SOD1G93A) showed neuromuscular junctions’ dismantlement, which is considered an early pathogenic signature of sarcopenia." (PMID 35276842, 2022). "SOD1−/− was also claimed to be a model of sarcopenia showing various signs of aging." (PMID 35883894, 2022). "For this reason, SOD1−/− mice have been used in various studies of muscle atrophy and sarcopenia." (PMID 36500717, 2022). "Finally, the acceleration of the fiber type shifts and mitochondrial dysfunction in i-mn-Sod1-/- mice support the possibility that neuronal redox homeostasis is key for maintaining muscle function and its disruption is a major initiator of sarcopenia." (PMID 34639076, 2021).
sarcopenia (continued). "Furthermore, in SOD1 mutant mice developing sarcopenia, treatment with Trolox was able to rescue mitochondrial function and subcellular organization, restore NMJ morphology, and return acetylcholine receptor turnover to age-matched WT levels." (PMID 34445751, 2021). "In the present study, through examination of mitochondrial function, excitation contraction (EC)-coupling, sarcopenia, and denervation throughout life in WT and i-mn-Sod1-/- mice, we provide insights into the sequential nature of the age-associated changes in these phenotypes." (PMID 34639076, 2021). "In a proteomics analysis of the muscles of a Sod1−/− mouse model of accelerated sarcopenia, enzymes participating in carbohydrate metabolism were downregulated in the case group, which may disrupt normal mitochondrial function and result in muscle mass loss." (PMID 35155487, 2021). "We observed that the expression of IL1B, BAK1 and SOD1 were significantly increased, while the expression of CDH1, GNG11 and ZAP70 were dramatically decreased in sarcopenia samples compared to those in the controls." (PMID 32226296, 2020). "Nitration of protein tyrosine residues (3-NT), as well as SOD1 and SOD2 (expression were both increased in skeletal muscle from aged mice, consistent with increased oxidative stress in sarcopenia." (PMID 26485763, 2015). "Muscle-specific deletion of Sod1 or a neuron-specific reduction in Sod1 in mice is not sufficient to initiate a full-blown sarcopenia phenotype." (PMID 40313092, 2026). "In a previous paper, we showed that nitration of protein tyrosine residues, as well as SOD-1 and SOD-2 expression, are both increased in the skeletal muscle of aged mice, and many authors also reported increased oxidative stress levels in sarcopenia." (PMID 41009681, 2025). "Accelerated sarcopenia is observed in transgenic mice lacking the antioxidant enzyme superoxide dismutase 1 (SOD1), which are characterized by diminished mitochondrial bioenergetic function." (PMID 40170675, 2025). "Previous studies demonstrate that mice lacking the SOD1 enzyme have elevated oxidative stress and display muscle weakness, denervation, and sarcopenia." (PMID 40136639, 2025). "We and others have previously demonstrated a mouse model of redox‐dependent sarcopenia, mice lacking superoxide dismutase 1 (Sod1), superoxide scavenger primarily localized in cytoplasm and intermembrane space." (PMID 35199907, 2022). "Thus, an accelerated manifestation of sarcopenia is seen in transgenic mice lacking the antioxidant enzyme superoxide dismutase 1 (SOD1), which are characterized by both a diminished mitochondrial bioenergetic function and an induction of mitochondrial-mediated apoptosis." (PMID 34362885, 2021). "Furthermore, while this study suggests that H2O2 is the key oxidant in the onset of sarcopenia, the lack of antioxidant protection from catalase and GPx is equally as important, whereas the lack of SOD1 antioxidant protection at 24 months does not appear to contribute to sarcopenia." (PMID 24093947, 2013). "The expression of SOD1, CAT, GR, and GS was significantly reduced in patients with sarcopenia compared to non-sarcopenic individuals." (PMID 38001845, 2023). "Interestingly, mice lacking Cu/Zn-superoxide dismutase (SOD1) display high levels of oxidative stress damage and early insurgence of sarcopenia; similar results are observed when SOD1 ablation is restricted to muscle tissue." (PMID 35276842, 2022).
kidney damage (39 papers, 2012 to 2025). "Most SOD activity in the mammalian kidney is through SOD1, which accounts for approximately 80%, and studies in animal models and humans have implicated reduced SOD1 activity in kidney damage." (PMID 32481548, 2020). "Multiple variations in cytosolic Zn-Cu SOD (SOD1) are significantly associated with severe nephropathy." (PMID 27471738, 2016). "The serum concentrations of blood urea nitrogen and creatinine, which represent parameters of kidney damage, were comparable between Sod1−/− and WT mice upon LCMV infection, suggesting a non-generalized pathogenesis that is primarily affecting the liver." (PMID 26588782, 2015). "In contrast, another study reported that high glucose induced increased mRNA expressions of SOD1, CAT and GPx in peripheral blood mononuclear cells of type I diabetic patients without microvascular complications and decreased expression of these enzymes was found in patients with nephropathy." (PMID 36818894, 2022). "To elucidate whether short-term PM2.5 exposure could induce kidney damage, we exposed BALB/c mice to PM2.5 intratracheally and measured the biomarkers of kidney injury (KIM-1, cystatin C), oxidative stress (MDA, SOD-1, and HO-1), and inflammatory response (NF-κB, TNF-α)." (PMID 30151074, 2018).
heart failure (38 papers, 2011 to 2025). Inability of the heart to pump blood at an adequate rate to meet tissue metabolic requirements. "Disturbed Cu metabolism has also been connected to ischemic heart disease and heart failure involving dysfunction of CP, SOD1, and SOD3 chaperones." (PMID 36818345, 2023). "Regulation of SOD, in particular SOD-1 (located in the cytosol), and SOD-2 (located in mitochondria), has been proven to attenuate hypertrophy and even more important transition to heart failure." (PMID 30618811, 2018). "Similar to other antioxidant enzymes, such as superoxide dismutase 1 (SOD1), glutathione peroxidase (GPX) 3, GPX4, and peroxidedoxin 1, the expression of NQO1 decreases heart failure." (PMID 38138580, 2023).
glioma (36 papers, 2006 to 2025). A benign or malignant brain and spinal cord tumor that arises from glial cells (astrocytes, oligodendrocytes, ependymal cells). "Consistent with this theory, polymorphisms in glutathione S-transferase and superoxide dismutase 1, two enzymes involved in ROS clearance, are among the few associated with increased glioma incidence." (PMID 38528608, 2024). "So we consider that the upregulation of SOD1 in glioma may be associated with the high levels of ROS." (PMID 35978820, 2022). "The results of SOD1 knockdown/knockout and the pharmacological SOD1 inhibition using ATN-224 demonstrated a significant influence of SOD1 on the adaptation of glioma cells to the tumor microenvironment." (PMID 39187509, 2024). "Although it is already known that SOD1 is upregulated in cancers, SOD1 function and its potential as therapeutic target have been poorly studied in glioma cells." (PMID 39187509, 2024). "We report that genetic and pharmacological inhibition of SOD1 leads to sensitization to hypoxia-induced cell death and disruption of redox balance under conditions of the glioma microenvironment." (PMID 39187509, 2024). "Our mechanistic studies indicated that enhanced SOD1 activity protects GB cells from conditions of the glioma microenvironment by maintaining redox homeostasis." (PMID 39187509, 2024). "Genetic and pharmacological inhibition of SOD1 correlated with decreased SOD1 activity, increased ROS and enhanced the sensitivity of glioma cells towards starvation- and hypoxia-induced cell death." (PMID 39187509, 2024). "By exploring mechanisms of action, potential synergies with mTORC1 inhibitors, and implications for glioma cell biology, we aim to highlight the potential benefits and challenges of targeting SOD1." (PMID 39187509, 2024). "Different concentrations of the inhibitor (0.01 μM to 10 μM) were tested in LN-229 and T98G glioma cells using the SOD1/2 activity assay." (PMID 39187509, 2024). "In present study SOD1 expression was found downregulated in gliomas compared to healthy control tissues which are in line with the previously reported findings." (PMID 36809279, 2023). "The aim of present study was to elucidate the role of expression deregulations of mitochondrial sirtuin genes and co-expression with their associated proteins (SOD1, SOD2, OGG1-2α, PARP1, GDH and HIF1α) in glioma." (PMID 36809279, 2023). "The results showed that SOD1 IHC scores were 224 ± 57, 294 ± 51, 238 ± 85, 281 ± 78, 308 ± 55, 314 ± 42 for normal tissues, glioma adjacent tissues, glioma grade I, II, III and IV tissues respectively." (PMID 35978820, 2022). "Statistical results showed that the expression scores of SOD1 in glioma grade III and IV tissues were significantly higher than that in brain normal tissues and glioma grade I tissues (P < 0.05)." (PMID 35978820, 2022). "U251 and U87 glioma cells expressed high levels of SOD1, low levels of SOD2 and very low levels of SOD3." (PMID 35978820, 2022). "qRT-PCR results showed that these two glioma cell lines expressed higher levels of SOD1, lower levels of SOD2, and very low levels of SOD3." (PMID 35978820, 2022). "The treatment of glioma cells with LCS-1 inhibits SOD1, resulting in the accumulation of ROS, leading to DNA damage." (PMID 35978820, 2022). "The radioresistance of human glioma cells induced by SOD1 overexpression is related to the inhibition of late ROS accumulation and enhancement of G2/M accumulation." (PMID 35935861, 2022). "In this study, SOD1 moderate staining was observed in normal brain tissues, glioma adjacent tissues, glioma grade I and II tissues, whereas SOD1 strong staining was found in glioma grade III, IV tissues." (PMID 35978820, 2022). "LCS-1 inhibition of SOD1 induced ROS-dependent cell death in glioma cells, and decreased glioma growth in vivo." (PMID 35978820, 2022). "In glioma cell lines, SOD1 inhibitor induced ROS production, activated ROS signaling, and increased SOD1 expression." (PMID 35978820, 2022).
glioma (continued). "In this study, we found that GPR17 increased ROS level in glioma cells through a regulation on SOD1 gene expression." (PMID 34120140, 2021). "Nevertheless, the expression levels of detoxifying enzymes such as Sod1 and Sod2 were reduced in both glioma cell lines." (PMID 34832864, 2021). "In this study, we found that brucine not only induced NOX4 activation but also upregulated the protein levels of NOX4 and SOD1 in glioma cells, knockdown of NOX4 with siRNA obviously prevented brucine-induced increases of superoxide and H2O2." (PMID 34112960, 2021). "Elevated expressions of superoxide dismutase 1 (SOD1) have been reported in human gliomas and thus conferred radioresistance." (PMID 25419901, 2014). "In glioma cells, SOD1 knockdown induces cell death through disruption of redox homeostasis." (PMID 40867898, 2025). "Treatment of glioma cells with rapamycin enhanced SOD1 activity." (PMID 39187509, 2024). "In comparison to OE-DNM1L and OE-FIS1, the impact of OE-MFF on mitophagy levels and SOD1 expression in glioma cells exhibited notable differences, further underscoring the distinct roles played by different molecules in modulating mitophagy and cellular oxidative states within glioma cells." (PMID 39350223, 2024). "For the first time we could demonstrate that SOD1 inhibition in glioma cells using the small molecule inhibitor ATN-224 sensitizes GB cells towards conditions of the tumor microenvironment including glucose and oxygen deprivation." (PMID 39187509, 2024). "However, in order to identify representative glioma cell lines for further experiments the basal expression of SOD1 and 2 was examined in different human (primary) GB cell lines and human astrocytes." (PMID 39187509, 2024). "Similarly, sh-FIS1 exhibited pronounced inhibitory effects on both mitophagy levels and SOD1 expression in glioma cells; conversely, OE-FIS1 elicited comparable positive regulatory effects as OE-DNM1L." (PMID 39350223, 2024). "Taking together, these results suggest that the degradation of both PARP and BRCA1 may contribute to cell death induced by SOD1 inhibition, and SOD1 may be a target for glioma therapy." (PMID 35978820, 2022). "The higher expression of SOD1 in glioma tissue may be due to the higher levels of ROS, which are derived from the aberrant metabolism." (PMID 35978820, 2022). "In this study, we found that clinical glioma expressed increased SOD1." (PMID 35978820, 2022). "In this study, we found that glioma tissues expressed high levels of superoxide dismutase 1 (SOD1)." (PMID 35978820, 2022). "Furthermore, overexpression of SOD1 correlates with radioresistance in human glioma cells." (PMID 39042641, 2024). "Thus, the current study is designed to investigate expression level of SIRT3, SIRT4, SIRT5 and associated genes SOD1, SOD2, OGG1-2α, PARP1, GDH and HIF1α in glioma patients and to find out whether this expressional deregulation effects the risk of glioma." (PMID 36809279, 2023). "However, less evidence is reported about the expression of SOD1 in gliomas." (PMID 35978820, 2022). "SOD isoforms, especially SOD2 and SOD1, have been shown in prior studies to have dual functions in glioma and glioblastoma by shielding tumor cells from oxidative stress and enhancing resistance to treatment." (PMID 40867576, 2025). "SOD1 is often overexpressed in non-small-cell lung cancer (NSCLC), breast cancer, glioma, and leukemia." (PMID 40867898, 2025). "To analyze potential prognostic effects of SOD1/2 in GB patients, we analyzed publicly available databases for SOD1 and SOD2 expression in gliomas." (PMID 39187509, 2024). "Forced expression of KLF9 inhibited glioma cell proliferation in vitro and tumor growth in vivo, in part, by suppressing expression of SOD1 (Superoxide Dismutase 1) and miR-21, the latter being a known pro-tumorigenic molecule." (PMID 38067370, 2023).